TSPO (translocator protein)
Diseases named in the same sentence as TSPO in open-access papers (continued):
Sharing a sentence is not in itself a finding about the gene and the disease.
tauopathy (continued). "However, our previous work in 4R-tauopathy indicated that signal elevation of cortical TSPO-PET is phenotype-dependent and regionally heterogeneous in individual patients, with maximum VOI differences of ~15% at the group level." (PMID 34073557, 2021). "Contrary, patients with 4RT showed high sTREM2 levels when regional TSPO-PET was associated with tau-PET (rs = 0.705, p = 0.034), which may indicate different trajectories of microglia phenotypes in the course of primary and secondary tauopathies." (PMID 37495886, 2023). "Furthermore, cross-breeding of Aβ and tauopathy mouse models with TSPO knock-out mice could mechanistically help elucidate the effect of sex differences of TSPO on functionally related pathways such as cholesterol synthesis." (PMID 33317543, 2020). "TSPO-PET levels were distinctly higher in primary and secondary tauopathies with MAB and HAB status when compared to a mixed cohort (n = 2 AD, n = 4 4RT, n = 1 healthy control) of low-affinity binders." (PMID 37495886, 2023). "Among others, our group has recently shown that elevated TSPO labeling in patients with CBS corresponds to the expected topology, and we demonstrated that [18F]GE-180 can detect neuroinflammation in 4R tauopathies, including CBS." (PMID 35203967, 2022). "However, despite several studies with tau and TSPO tracers, ATI(N)-like schemes and interactions have only rarely been investigated in atypical AD or primary tauopathies, although Aβ copathology is common in 4RTs." (PMID 37495886, 2023). "TSPO PET has been used for imaging neurodegenerative diseases, mostly in Alzheimer’s disease, β-amyloid mouse models and less frequently in 4R-tauopathies, reporting pronounced subcortical neuroinflammation." (PMID 35203967, 2022). "In vivo neuroimaging results were confirmed by immunohistochemistry for markers of neuronal survival (NeuN), tauopathy (AT8), and inflammation (TSPO, ionized calcium-binding adaptor molecule 1 or IBA-1, and complement component 1q or C1q) in brain sections from scanned mice." (PMID 33740987, 2021). "In this way, the neuroinflammatory process has been proposed as possible diagnostic tools, through in vivo uptake of the microglia, using positron emission tomography (PET) images with the translocator protein (TSPO) ligand [11C]-PK11195 in the FTD and other tauopathies." (PMID 31572186, 2019). "Furthermore, the neuroinflammatory process has been proposed as a potential diagnostic tool through the in vivo evaluation of microglial activation, using DLB imaging with the translocator protein (TSPO) ligand [11C]-PK11195 in FTD and other tauopathies." (PMID 29570615, 2018). "Because of the discrepancies between various genetic models used to study the TSPO gene in mice, this study has investigated the interactions between oxidative damage, microglia, and tauopathy in humans without losing sight of the importance of single nucleotide polymorphisms." (PMID 32842621, 2020). "This study had two principal aims: (i) to test the hypothesis that TSPO elevation in tauopathies is microglial-specific, rather than driven by astrocytes; and (ii) to test the hypothesis that ante-mortem TSPO PET imaging correlates with regional and individual post-mortem differences in microglia." (PMID 40036275, 2025). "Thus, the synthesis of our combined findings comprise strong evidence for a sex-specific effect on the TSPO-PET signal in aging wild-type mice, and the association between microglia activation with Aβ accumulation in transgenic mice, without corresponding association with tauopathy in P301S mice." (PMID 33317543, 2020).
Huntington disease (15 papers, 2013 to 2025). Huntington disease (HD) is a rare neurodegenerative disorder of the central nervous system characterized by unwanted choreatic movements, behavioral and psychiatric disturbances and dementia. "Over 1 year, regional TSPO expression (reflected by 11C-PBR28 PET-CT DVRs) was different in the brains of Huntington’s disease participants." (PMID 37020532, 2023). "Other PET tracers have been tested, including 11C-PBR28, to label 18kDA translocator protein (TSPO), which is known to label glial cells and has been utilized in a variety of disease states, including Huntington’s Disease." (PMID 35203515, 2022). "This well-known model of Huntington's diseases has recently been shown to be useful to study the overexpression of the translocator protein (TSPO) as a relevant marker of neuroinflammation." (PMID 23533686, 2013). "Furthermore, in manifest HD patients, the correlation between striatal TSPO tracer binding and the severity of motor symptoms (evaluated by the unified Huntington’s disease rating scale) could echo the ex vivo relationship found between neuronal loss and density of reactive microglia." (PMID 28387722, 2017). "The data from the PET-CT study of the LEGATO-HD trial show that TSPO expression in the caudate and putamen does not change significantly over 1 year in patients with Huntington’s disease." (PMID 37020532, 2023).
rheumatoid arthritis (14 papers, 2017 to 2025). A chronic, systemic autoimmune disorder characterized by inflammation in the synovial membranes and articular surfaces. "Association between TSPO and inflammation is not only restricted to observations made in the colon; TSPO upregulation has been reported in conditions that induce neuroinflammation, cardiovascular inflammation, and rheumatoid arthritis." (PMID 36060674, 2022). "High TSPO levels are also found, for example, in macrophages in cases of rheumatoid arthritis and in malignant tumor cells compared to their relatively low physiological expression." (PMID 38139248, 2023). "Significantly higher uptake of [11C]MC1 (COX-2) and [11C]ER176 (TSPO) was observed in the hand, elbow, and/or shoulder joints of two individuals with rheumatoid arthritis compared to other joints in the same individuals as well as in the corresponding joints of two healthy controls." (PMID 32359360, 2020). "Here, we utilized three human sources of monocyte derived macrophages (MDM), from THP-1 monocytes, healthy peripheral blood monocytes and synovial fluid monocytes from patients with rheumatoid arthritis, to undertake a detailed investigation of TSPO expression in activated macrophages." (PMID 28968465, 2017). "Positron emission tomography (PET) imaging of macrophages using the translocator protein (TSPO) tracer (R)-[11C]PK11195 has shown the promise to image rheumatoid arthritis (RA)." (PMID 31553762, 2019). "It was later found that TSPO targeted imaging could be utilized for the imaging of non-neuronal inflammatory diseases such as rheumatoid arthritis (RA), atherosclerosis, Takayasu arteritis (TAK), systemic lupus erythematosus (SLE), and GCA." (PMID 35733858, 2022). "Although not shown in this study, it has been reported that TSPO is as well expressed by CD4+ lymphocytes in EAE, as it is in humans and in a model of rheumatoid arthritis." (PMID 30696113, 2019).
atherosclerosis (13 papers, 2014 to 2024). A disease characterized by the build-up of fatty material and calcium deposition in the arterial wall resulting in partial or complete occlusion of the arterial lumen. "Becauseactivated macrophages express high TSPO levels, TSPO radioligands could represent valuable tools for detectinginflammation associated with atherosclerosis by PET." (PMID 38113353, 2024). "Therefore, TSPO hyperactivity in this specific region may be particularly relevant to evaluate high-risk atherosclerosis." (PMID 33937770, 2021). "In one study, LSFM was combined with PET/CT imaging to investigate the localization of translocator protein (TSPO) in atherosclerotic lesions for the progression of atherosclerosis." (PMID 39728300, 2024). "We preclinically evaluated 18F-GE-180, a novel third-generation TSPO radioligand, in a mouse model of atherosclerosis." (PMID 29950954, 2018). "As an imaging target for atherosclerosis, TSPO is attractive since it is highly expressed in macrophages." (PMID 29950954, 2018). "Furthermore, PET imaging using TSPO has also been reported to have shown promising results in atherosclerosis detection, 3H-DAA1106 ((N-5-fluoro-2-phenoxyphenyl)-N-(2,5-dimethoxybenzyl)acetamide), 3H-(R)-PK11195, and 11C-PK11195 being such examples." (PMID 35563414, 2022). "We indeed also observed impaired CP TSPO activity together with decrease gadolinium enhancement which could sign the chronic systemic inflammation in these aged animals with diet-induced atherosclerosis." (PMID 33937770, 2021). "The high level of TSPO in plaque macrophagesis represents a diagnostic tool in atherosclerosis through noninvasive PET imaging so it can predict the morphology and pathogenesis of pre-rupture atherosclerosis based on TSPO." (PMID 33799869, 2021). "Because the TSPO levels in vascular disease conditions such as atherosclerosis remain unknown, it will be therefore valuable to investigate its expression." (PMID 30741928, 2019). "Of note, because TSPO expression in non-myocyte populations (namely macrophages) increases markedly during inflammation, TSPO serves as powerful biomarker in diabetes mellitus, atherosclerosis and other inflammatory diseases in an ever-growing number of PET studies." (PMID 30416455, 2018). "Beyond this potential diagnostic role of TSPO PET scanning for atherosclerosis, TSPO might be used as a therapeutic target for atherosclerosis." (PMID 29114179, 2017). "However, despite human TSPO polymorphism, the potential for 11C-PBR28 PET for assessments of human AAA development, atherosclerosis, and vasculitis appears to be significant." (PMID 26055934, 2014).
Cerebral ischemia (13 papers, 2012 to 2022). Restriction of arterial blood supply to the brain associated with insufficient oxygenation to support the metabolic requirements of the tissue. "Our study demonstrates that AChE level is elevated in the early course of brain ischemia as a trigger for the inflammatory response, and TSPO level is elevated persistently throughout the post-ischemic injury in the brain." (PMID 34072449, 2021). "In fact, these results stand in agreement with the in vivo PET imaging distribution of TSPO, a well-known marker of neuroinflammation, after cerebral ischemia." (PMID 32848565, 2020). "For example, overexpression of TSPO in the monocytic lineage as well as astrocytes that follows focal cerebral ischemia can be imaged with PET of the second-generation TSPO-selective radioligand 18F-DPA-714." (PMID 32252470, 2020). "In vivo positron-emission tomography (PET) imaging of transporter protein (TSPO) expression is an attractive and indispensable tool for the diagnosis and therapy evaluation of neuroinflammation after cerebral ischemia." (PMID 29177913, 2017). "[18F] VUIIS1008 and [18F] DPA-714 PET signals showed higher uptake in hyperintense lesions on T2W-MRI images evidencing the expression of TSPO following cerebral ischemia." (PMID 29177913, 2017). "The purpose of the present study was to investigate the usefulness of the novel radiotracer [18F] VUIIS1008 to monitor TSPO expression following a preclinical model of cerebral ischemia." (PMID 29177913, 2017). "Cerebral ischemia leads to an overexpression of TSPO which has been considered as a sensitive marker related to the size of the brain lesion and clinical outcome." (PMID 29177913, 2017). "Likewise, after brain injury induced by focal cerebral ischemia, both microglia and astrocytes have been found to overexpress TSPO, with a dissimilar distribution within the infarcted lesion." (PMID 28387722, 2017). "In addition, the fact that [18F] DPA-714 could successfully displace [18F] VUIIS1008 supports the specificity of this latter to bind to TSPO in vivo following cerebral ischemia." (PMID 29177913, 2017). "Here, we prove TSPO PET is a valuable tool for detecting acute and chronic neuroinflammation in cerebral ischemia." (PMID 29976695, 2019). "Here, we report the first, to our knowledge, head-to-head comparison of 2 promising second-generation TSPO tracers, 11C-DPA-713 and 18F-GE-180, in a rodent model of cerebral ischemia." (PMID 29976695, 2019). "We report here the PET imaging of TSPO with both [18F] VUIIS1008 and [18F] DPA-714 in a rat model of cerebral ischemia." (PMID 29177913, 2017). "The evaluation of TSPO expression was assessed with immunohistochemistry at different magnifications in the contralateral hemisphere and the core of the infarction, as represented in the co-registered [18F] VUIIS1008 PET-MRI T2W image at day 7 after cerebral ischemia (20×*, 20×** and 100×**)." (PMID 29177913, 2017).
ischemia (13 papers, 2014 to 2024). A hypoperfusion of the BLOOD through an organ or tissue caused by a PATHOLOGIC CONSTRICTION or obstruction of its BLOOD VESSELS, or an absence of BLOOD CIRCULATION. "Our results show that 18 F-DPA-714 uptake after acute ischemia is mainly associated with TSPO expression in the infarct area and in the surrounding neighbourhood." (PMID 25006546, 2014). "Here, we showed a transient decrease in TSPO expression within the infarct in PLX5622-treated mice but a continuous decrease in healthy tissue from day 14 after ischemia." (PMID 34168016, 2022). "In fact, this is the first study using PET imaging to evaluate the modulatory effect of A1ARs on neuroinflammation after ischemia using TSPO as biomarker of reactive gliosis." (PMID 33391483, 2021). "Previous in vivo PET imaging of TSPO with [18F] DPA-714 showed low levels of the PET signal before the ischemia onset evidencing the low expression of TSPO in the healthy cerebral tissue." (PMID 29177913, 2017). "This study investigated the effect of a TSPO agonist, etifoxine, on neuroinflammation and brain injury after ischemia/reperfusion." (PMID 28754131, 2017). "A potential explanation for the surprising increase in ROS when PK11195 was given during ischemia could be an enhanced mitochondrial Ca2+ accumulation as a consequence of TSPO inhibition." (PMID 34149440, 2021). "Therefore, the current findings suggest that TSPO imaging might be useful for detection of neuroinflammation leading to SNL after mild ischemia as well as severe ischemia." (PMID 29884977, 2018). "The brains were double stained for TSPO and Iba-1 or GFAP or F4/80 at day 35 post ischemia to identify the cellular sources of TSPO." (PMID 33754046, 2021). "[18F]DPA-714 (TSPO, neuroinflammation marker) PET-CT scans were acquired at days 7, 14, 21 and 30 post ischemia." (PMID 33754046, 2021). "In the brain sections of the ischemia group, the fluorescence intensity for MAGL was lower in the cerebral cortex and striatum of the ipsilateral side, whereas fluorescence signals for TSPO were enhanced in the same regions, strongly suggesting the degeneration of neurons." (PMID 34646382, 2021).
bipolar disorder (11 papers, 2013 to 2024). A disorder of the brain that causes unusual shifts in mood, energy, activity levels and the ability to carry out day-to-day tasks. "Gene variants such as the rs6971 TSPO polymorphism, which affects ligand binding and cholesterol uptake, were found to be linked to both bipolar disorder in general and diurnal cortisol rhythm in bipolar disorder." (PMID 38650030, 2024). "This is consistent with findings that TSPO deletion in rodents and its corresponding rs6971 polymorphism in humans has recently been associated with diurnal variation (morning versus evening in cortisol levels in saliva in patients with bipolar disorder and AUD." (PMID 29777199, 2018). "A mutual dependence between TSPO and VDAC expression is also demonstrated in patients with bipolar disorder who exhibited significantly increased expression levels of both TSPO and VDAC in their peripheral blood mononuclear cells (PBMCs)." (PMID 39684592, 2024). "For bipolar disorder, an increase of TSPO mRNA and protein together with inflammasome activation was found in peripheral blood monocytes." (PMID 33433698, 2021). "Structural changes to the TSPO protein may be clinically impactful in humans with bipolar disorder and stress-exacerbated disease." (PMID 35893041, 2022). "TSPO upregulation is concomitant with NLRP3 inflammasome activation in bipolar disorder." (PMID 33542692, 2020). "The presence of this TSPO polymorphism was linked to reduced pregnenolone and adrenocorticotropic hormone (ACTH)-induced corticosteroid levels and shown to be associated with dysregulated cortisol rhythms and consequent clinical exacerbations in bipolar disorders." (PMID 33433698, 2021). "Although we saw no change in microglial TSPO gene expression in bipolar disorder, future work should examine TSPO expression in psychiatric disorders in more detail." (PMID 37640701, 2023).